UPF1 (UPF1 RNA helicase and ATPase)
Description:
RNA-dependent helicase required for nonsense-mediated decay (NMD) of aberrant mRNAs containing premature stop codons and which modulates the expression level of normal mRNAs. ATP-dependent 5'-3' helicase active on RNA:DNA substrates with a 5'-RNA extension. ATP-dependent 5'-3' helicase active on RNA:RNA substrates with a 5'-RNA extension. ATP-dependent 5'-3' helicase active on DNA:DNA substrates with a 5'-DNA extension. Is recruited to mRNAs upon translation termination and undergoes a cycle of phosphorylation and dephosphorylation; its phosphorylation appears to be a key step in NMD. Recruited by release factors to stalled ribosomes together with the SMG1C protein kinase complex to form the transient SURF (SMG1-UPF1-eRF1-eRF3) complex. In EJC-dependent NMD, the SURF complex associates with the exon junction complex (EJC) (located 50-55 or more nucleotides downstream from the termination codon) through UPF2 and allows the formation of an UPF1-UPF2-UPF3 surveillance complex which is believed to activate NMD. Phosphorylated UPF1 is recognized by EST1B/SMG5, SMG6 and SMG7 which are thought to provide a link to the mRNA degradation machinery involving exonucleolytic and endonucleolytic pathways, and to serve as adapters to protein phosphatase 2A (PP2A), thereby triggering UPF1 dephosphorylation and allowing the recycling of NMD factors. UPF1 can also activate NMD without UPF2 or UPF3, and in the absence of the NMD-enhancing downstream EJC indicative for alternative NMD pathways. Plays a role in replication-dependent histone mRNA degradation at the end of phase S; the function is independent of UPF2. For the recognition of premature termination codons (PTC) and initiation of NMD a competitive interaction between UPF1 and PABPC1 with the ribosome-bound release factors is proposed. The ATPase activity of UPF1 is required for disassembly of mRNPs undergoing NMD. Together with UPF2 and dependent on TDRD6, mediates the degradation of mRNA harboring long 3'UTR by inducing the NMD machinery (By similarity). Has ssDNA-stimulated ATPase activity (poly(dT) and poly(dA) are most stimulatory). Binds RNA; addition of ATP decreases RNA-binding.
Synonyms: NORF1; hUpf1; KIAA0221; RENT1; pNORF1; smg-2; UTF
Tractability: Small molecule: a structure with a bound ligand is known; it has a high-quality binding pocket. PROTAC: ubiquitination databases record sites on it; its protein half-life has been measured.
Target class: Enzyme; Hydrolase
Gene: Protein-coding gene on chromosome 19 (18,831,905 to 18,868,232, forward strand). Ensembl gene ENSG00000005007.
Subcellular location: Cytoplasm; Cytoplasm, P-body; Nucleus; Cytoplasm, perinuclear region
Subcellular location (Human Protein Atlas): Nucleoplasm; Cytosol
Pathways (Reactome):
Metabolism of RNA: Nonsense Mediated Decay (NMD) enhanced by the Exon Junction Complex (EJC); Nonsense Mediated Decay (NMD) independent of the Exon Junction Complex (EJC)
Gene Ontology:
Molecular function: 5'-3' DNA helicase activity; 5'-3' DNA/RNA helicase activity; 5'-3' RNA helicase activity; ATP hydrolysis activity; chromatin binding; double-stranded DNA helicase activity; protein binding; protein-containing complex binding; RNA binding; RNA helicase activity; telomeric DNA binding; helicase activity; ATP binding; DNA binding; hydrolase activity; zinc ion binding
Biological process: 3'-UTR-mediated mRNA destabilization; cell cycle phase transition; DNA repair; DNA replication; histone mRNA catabolic process; nuclear-transcribed mRNA catabolic process; nuclear-transcribed mRNA catabolic process, nonsense-mediated decay; positive regulation of mRNA catabolic process; regulation of telomere maintenance; regulation of translational termination; telomere maintenance via semi-conservative replication; cellular response to interleukin-1; cellular response to lipopolysaccharide; mRNA export from nucleus; negative regulation of nuclear-transcribed mRNA catabolic process, nonsense-mediated decay; positive regulation of nuclear-transcribed mRNA catabolic process, nonsense-mediated decay; RNA surveillance; positive regulation of mRNA metabolic process; regulation of gene expression
Cellular component: chromatin; chromosome, telomeric region; cytoplasm; cytosol; exon-exon junction complex; nucleoplasm; nucleus; supraspliceosomal complex; nonsense-mediated decay complex; P-body; perinuclear region of cytoplasm
Genetic constraint (gnomAD): Loss-of-function variants: 9 observed, 125.49 expected, observed/expected ratio (o/e) 0.0717, 90% interval 0.042 to 0.12. The upper end of that interval is the gene's LOEUF score, 0.12, which puts it in group 1 of 6, group 1 being the genes least tolerant of losing a copy. Missense variants: 788 observed, 1,518.4 expected, observed/expected ratio (o/e) 0.52, 90% interval 0.49 to 0.55. Synonymous variants: 649 observed, 637.45 expected, observed/expected ratio (o/e) 1.02, 90% interval 0.95 to 1.09.
Homologues: Orthologues: chimpanzee UPF1 (100% identical), macaque UPF1 (100% identical), dog UPF1 (99% identical), pig UPF1 (99% identical), mouse Upf1 (98% identical), rat Upf1 (98% identical), guinea pig UPF1 (97% identical), tropical clawed frog upf1 (95% identical), zebrafish upf1 (94% identical), Drosophila melanogaster Upf1 (66% identical), Caenorhabditis elegans smg-2 (48% identical). Paralogues in human: HELZ2 (24% identical), SETX (19% identical), IGHMBP2 (15% identical), HELZ (14% identical), ZNFX1 (14% identical), MOV10L1 (14% identical), DNA2 (13% identical), MOV10 (13% identical), AQR (12% identical), CT55 (1% identical).
Diseases named in the same sentence as UPF1 in open-access papers:
UPF1 is named in the same sentence as 79 diseases in open-access papers, as found by Europe PMC text mining. Sharing a sentence is not in itself a finding about the gene and the disease. The quoted sentences say what the papers report.
hepatocellular carcinoma (22 papers, 2016 to 2026). A malignant tumor that arises from hepatocytes. "In this study, we revealed that UPF1 regulates the abundance of hepatocellular carcinoma upregulated EZH2-associated lncRNA (lncRNA-HEIH) by binding the CG-rich motif, thereby regulating hepatocellular carcinoma (HCC) tumorigenesis." (PMID 38297160, 2024). "For example, the high mutation rate of Upf1 in pancreatic adenosquamous carcinoma and its downregulation in hepatocellular carcinoma indicate that the NMD pathway could be frequently suppressed." (PMID 28874147, 2017). "In another study, it was shown in hepatocellular carcinoma (HCC) that downregulation of UPF1, due to promoter hypermethylation, inhibited NMD and upregulated expression of SMAD7." (PMID 36833284, 2023). "In previous studies, UPF1 was found to be significantly down regulated in pancreatic cancer, hepatocellular carcinoma (HCC), gastric cancer (GC), thyroid cancer (TC) and glioma, and was verified in most cell lines of these cancers." (PMID 36421841, 2022). "In this study, UPF1 deletion proteins had comparable functions in hepatocellular carcinoma inhibition to full-length UPF1, which would allow UPF1 variants to be employed for therapeutic approaches in hepatocellular carcinoma." (PMID 35453543, 2022). "Knockdown of UCA1 ameliorated the effect of UPF1 knockdown on HCC growth and invasion, indicating that UCA1 mediates the effect of UPF1 on the invasion and proliferation of hepatocellular carcinoma cells." (PMID 33732285, 2021). "Previous studies showed that UPF1 inhibits the hepatocellular carcinoma progression by targeting MRP2/ABCC2 or long non-coding RNA UCA1." (PMID 34922601, 2021). "In the present study, we demonstrated that UPF1 expression was significantly reduced in hepatocellular carcinoma (HCC) tissues compared with the adjacent normal tissues." (PMID 31040354, 2019). "To investigate the expression and clinical significances of UPF1 in Hepatocellular Carcinoma (HCC), we first measured UPF1 expression in 50 cancer tissues and paired adjacent noncancerous HCC tissues." (PMID 31040354, 2019). "UPF1 is upregulated when SNHG6 is knocked down in human hepatocellular carcinoma cell lines." (PMID 33732285, 2021). "Herein, we examined the expression profiles of snoRNAs regulated by Upf1 in hepatoma cells." (PMID 32802196, 2020). "In order to evaluate whether CDKN1A mRNA was similarly regulated in hepatocellular carcinoma cells, we knocked down UPF1 in HepG2 cells and found upregulated p21 protein levels and CDKN1A mRNA levels." (PMID 31732746, 2019). "The fact that UPF1 expression retarded HCC growth is beneficial in gene therapy for hepatocellular carcinoma." (PMID 35453543, 2022). "In this study, we demonstrated that UPF1 expression was significantly reduced in hepatocellular carcinoma (HCC) tissues compared with the adjacent normal tissues." (PMID 31040354, 2019). "In hepatocellular carcinoma (HCC), it interacts with UPF1 and activates Wnt/β-catenin signaling, maintaining stemness and promoting proliferation." (PMID 41550840, 2026). "In recent years, SNAI3-AS1 has been reported to promote the proliferation and metastasis of hepatocellular carcinoma possibly by regulating the PEG10, UPF1 and TGF-β signaling pathway." (PMID 37173373, 2023). "Recent studies have shown an interplay between UPF1 and ILF3 in regulating each other in hepatocellular carcinoma." (PMID 35927743, 2022). "Similarly, lung adenocarcinomas (ADCs) and hepatocellular carcinomas (HCCs) display lower expression of UPF1 when compared to normal tissues due to promoter hypermethylation, a finding that correlates with poor prognosis in patients with HCC." (PMID 33926465, 2021). "UPF1 regulates tumor progression via diverse mechanisms across different kinds of cancers, including CRC, hepatocellular carcinoma, pancreatic adenosquamous carcinoma, glioblastoma, and endometrial carcinoma." (PMID 33193701, 2020).
hepatocellular carcinoma (continued). "In hepatocellular carcinoma (HCC), RBM47 upregulation significantly inhibits tumor progression in vitro, primarily through the upregulation of UPF1, serving as a tumor suppressor by acting as a DNA/RNA binding protein at both transcriptional and post-transcriptional levels." (PMID 39659787, 2024). "Several studies have indicated that UPF1 is downregulated and related to poor prognosis in pancreatic adenosquamous carcinoma (PASC), hepatocellular carcinoma (HCC), gastric cancer (GC), inflammatory myofibroblastic tumors (IMT), thyroid cancer (TC), ovarian cancer (OC) and glioma." (PMID 36421841, 2022). "UPF1 can prevent cancer stem cell (CSC)-like properties and inhibit the epithelial-mesenchymal transition (EMT) process via decreasing ABCC2 expression in hepatocellular carcinoma (HCC)." (PMID 35871061, 2022). "In vitro, UPF1 expression is decreased in hepatoma cells compared with normal liver cells." (PMID 26759305, 2016).
lung adenocarcinoma (12 papers, 2019 to 2024). A carcinoma that arises from the lung and is characterized by the presence of malignant glandular epithelial cells. "LncRNA ZFPM2‐AS1 attenuated the stability of ZFPM2 mRNA to inhibit ZFPM2 expression via interacting with RBP UPF1, thus promoting the progression of lung adenocarcinoma progression." (PMID 39425009, 2024). "In glioblastoma and lung adenocarcinoma, the authors illuminated that UPF1 functioned through the interacting with some LncRNAs." (PMID 34520393, 2021). "For instance, lncRNA ZFPM2-AS1 promotes lung adenocarcinoma progression by interacting with UPF1 to destabilize ZFPM2." (PMID 33102579, 2020). "The illustration of lncRNA ZFPM2‐AS1 promoted lung adenocarcinoma progression through cofunctioning with UPF1 to destabilize ZFPM2." (PMID 31919993, 2020). "Controversially, UPF1 was also found highly expressed in glioblastoma and lung adenocarcinoma." (PMID 36421841, 2022). "Inversely, UPF1 was highly expressed in glioblastoma and lung adenocarcinoma." (PMID 34520393, 2021). "UPF1 was expressed at lower levels in human lung adenocarcinoma tissues than in normal lung tissues, thereby raising the possibility that NMD may be downregulated to permit lung adenocarcinoma oncogenesis." (PMID 31040354, 2019). "The as-lncRNA ZFPM2-AS1 downregulates the expression of the tumour suppressor gene ZFPM2 through its interaction with UPF1 and promotes the proliferation, invasion, and EMT of lung adenocarcinoma cells, thus promoting the progression of lung adenocarcinoma." (PMID 37189431, 2023). "The GEPIA2 analysis results suggested that UPF1 show low expression in various tumors including Kidney Clear Cell Carcinoma (KIRC), Lung Adenocarcinoma (LUAD), Ovarian Cancer (OV), Melanoma (SKCM) and Testicular Cancer (TGCT)." (PMID 36421841, 2022). "UPF1 can bind to the 3′ UTR region of ZFPM2-AS1 and ZFPM2 mRNA, and forms a binding complex in lung adenocarcinoma cells." (PMID 33732285, 2021). "In this study, we found that UPF1 plays an oncogenic role in EEC like in glioblastoma and lung adenocarcinoma." (PMID 34520393, 2021). "IHC experiments, which were conducted in a cohort of patients presenting lung adenocarcinomas, showed high GABARAPL1 and low UPF1 levels in EMT+ tumors." (PMID 34680418, 2021). "The synergistic effect of ZFPM2-AS1 and UPF1 destroys the stability of ZFPM2 mRNA, down-regulates the expression of ZFPM2, and promotes the proliferation, invasion, and EMT of lung adenocarcinoma cells." (PMID 33732285, 2021). "Through interaction with UPF1 to promote ZFPM2 mRNA decay, ZFPM2-AS1 could promote lung adenocarcinoma (LUAD) cell growth, migration, and the epithelial-mesenchymal transition process, thus exerting oncogenic functions." (PMID 35993327, 2022). "Cao and colleagues found that UPF1 may inhibit TGF-β signaling by decreased expression of Smad2/3, MIXL1 and SOX17 in lung adenocarcinoma." (PMID 34922601, 2021).
gastric cancer (10 papers, 2009 to 2024). A primary or metastatic malignant neoplasm involving the stomach. "In CSTA a heterozygous mutation was detected in both GP202 and IPA220 gastric cancer cells transfected with UPF1 siRNA, at position 298 (mRNA seq." (PMID 19563644, 2009). "Only the last mutation was detected in the GP202 gastric cancer cells transfected with UPF1 siRNA, but this was a heterozygous mutation." (PMID 19563644, 2009). "In PLA2G4A, a mutation was detected in the UPF1 siRNA-transfected GP202 gastric cancer cells, at position 1012 (mRNA seq NM_024420.1) resulting in a C to T substitution at position 303 of the protein, but this mutation did not result in a different amino acid (GAC to GAT (Aspartate))." (PMID 19563644, 2009). "In PTPRJ, three mutations were detected in the UPF1 siRNA-transfected IPA220 gastric cancer cells." (PMID 19563644, 2009). "The UPF1 putative promoter region possesses an enriched CpG island in gastric cancer (GC), which was proved to be hypermethylated." (PMID 36766761, 2023). "The UPF1 inhibition of gastric cancer progression was reduced by high levels of MALAT1, demonstrating a promising target for gastric cancer treatment." (PMID 36766761, 2023). "In contrast, UPF1 inhibited the expression of MALAT1 in gastric cancer by accelerating its degradation." (PMID 35318304, 2022). "Researchers have demonstrated that UPF1 inhibits the expression of MALAT1 in gastric cancer and inhibits tumor development by targeting MALAT1." (PMID 34520393, 2021). "Using the siRNA strategy, UPF1 expression was repressed by >70% for the GP202 gastric cancer cell line (73% 74% and 71% for the biological replicates), and >80% for the IPA220 gastric cancer cell line (82%, 86% and 84% for the biological replicates)." (PMID 19563644, 2009). "UPF1 is highly expressed in a variety of cancers, such as glioblastomas, and low expression levels of UPF1 were documented in other types of tumors, such as gastric cancer, which suggest that UPF1 has pro- and antitumor effects." (PMID 35318304, 2022). "Notably, the expression level of UPF1 was found to be lowered in hepatocellular carcinoma tissues and gastric cancer compared to normal controls." (PMID 34520393, 2021). "The expression of UPF1 is negatively correlated with the expression of MALAT1 in gastric cancer." (PMID 33732285, 2021). "However, in the UPF1 siRNA-transfected GP202 gastric cancer cells, the first 196 bp of the coding sequence was missing due to PCR failures." (PMID 19563644, 2009). "UPF1 binds to MALAT1 and promotes its degradation, thereby inhibiting the expression of MALAT1 in gastric cancer." (PMID 33732285, 2021). "UPF1 expression was reduced for >70% and >80% in the GP202 and IPA220 gastric cancer cell lines, respectively." (PMID 19563644, 2009). "In addition, up-frameshift protein 1(UPF1) may regulate MALAT1, and the UPF1/MALAT1 pathways might potentially serve as a promising area of therapeutic exploration for the treatment of gastric cancer." (PMID 39346921, 2024). "Two non-commercial gastric cancer cell lines, GP202 and IPA220, were transfected with siRNA directed against UPF1, to specifically inhibit the nonsense mediated decay (NMD) pathway, and with siRNA directed against non-specific siRNA duplexes (CVII) as a control." (PMID 19563644, 2009).
lung carcinoma (10 papers, 2014 to 2024). "The decreased MARVELD1 level in lung cancer reduces NMD efficiency through diminishing the association between NMD complex component UPF1/SMG1 and premature termination codons containing mRNA (PTC-mRNA)." (PMID 25520033, 2014). "The missense mutation rate of UPF1 or UPF2 was higher in lung cancer." (PMID 35993327, 2022). "Analysis of other cancer types using TCGA has shown a similar selectivity to ovarian cancer; in lung cancer or esophageal cancer, the total amplification rate was lower than that for ovarian cancer, but the missense mutation rate was higher in either UPF1 or UPF2." (PMID 31718065, 2019). "Our results indeed confirmed that the levels of the key NMD factor UPF1 were downregulated in patients presenting with lung cancers with high levels of VIMENTIN, a key marker of the EMT." (PMID 34680418, 2021). "In lung cancer cells, Nanopore sequencing was also used to evaluate the impact of knocking down UPF1 on specific mRNA targets." (PMID 34389041, 2021). "In lung cancer, long noncoding RNA MACC1-AS1 was described to promote stemness through promoting UPF1-mediated destabilization of LATS1/2." (PMID 38339354, 2024). "LncRNA ZFPM2-AS1 interacts with UPF1 to destabilize ZFPM2, which promotes the advancement of lung cancer." (PMID 36267408, 2022). "Moreover, we constructed the NMD reporter plasmid expressing PTC-containing truncated LRP1B-GFP mRNA (LRP1B exons 1–9 from lung cancer cell line QG56), and demonstrated that MARVELD1 bound PTC-mRNA as efficient as NMD core factor UPF1 and SMG1 by RNA-ChIP based reporter system." (PMID 25520033, 2014).